GPT2 (glutamic--pyruvic transaminase 2)
Description:
Catalyzes the reversible transamination between alanine and 2-oxoglutarate to form pyruvate and glutamate.
Synonyms: ALT2; GPT 2; MRT49; NEDSPM
Tractability: PROTAC: ubiquitination databases record sites on it; its protein half-life has been measured.
Gene: Protein-coding gene on chromosome 16 (46,882,857 to 46,931,298, forward strand). Ensembl gene ENSG00000166123.
Subcellular location (Human Protein Atlas): Mitochondria
Pathways (Reactome):
Metabolism: Alanine metabolism
Gene Ontology:
Molecular function: L-alanine:2-oxoglutarate aminotransferase activity; pyridoxal phosphate binding; transaminase activity
Biological process: 2-oxoglutarate metabolic process; L-alanine biosynthetic process; L-alanine catabolic process
Cellular component: mitochondrion; mitochondrial matrix; cytoplasm
Genetic constraint (gnomAD): Loss-of-function variants: 24 observed, 49.83 expected, observed/expected ratio (o/e) 0.48, 90% interval 0.35 to 0.68. The upper end of that interval is the gene's LOEUF score, 0.68, which puts it in group 2 of 6, group 1 being the genes least tolerant of losing a copy. Missense variants: 503 observed, 657.84 expected, observed/expected ratio (o/e) 0.76, 90% interval 0.71 to 0.82. Synonymous variants: 256 observed, 266.27 expected, observed/expected ratio (o/e) 0.96, 90% interval 0.87 to 1.07.
Gene-disease validity (ClinGen):
ClinGen rates the evidence that GPT2 causes each of these diseases.
glutamate pyruvate transaminase 2 deficiency (autosomal recessive): Definitive.
Homologues: Orthologues: chimpanzee GPT2 (99% identical), pig GPT2 (97% identical), mouse Gpt2 (93% identical), guinea pig GPT2 (92% identical), macaque GPT2 (89% identical), dog GPT2 (85% identical), tropical clawed frog gpt2 (79% identical), rabbit GPT2 (79% identical), rat Gpt2 (75% identical), zebrafish gpt2 (70% identical), Drosophila melanogaster CG1640 (51% identical), Caenorhabditis elegans C32F10.8 (49% identical), and 3 more. Paralogues in human: GPT (63% identical), TAT (19% identical), KYAT1 (16% identical), ACCSL (15% identical), ACCS (15% identical), KYAT3 (15% identical), AADAT (13% identical).
Diseases named in the same sentence as GPT2 in open-access papers:
GPT2 is named in the same sentence as 74 diseases in open-access papers, as found by Europe PMC text mining. Sharing a sentence is not in itself a finding about the gene and the disease. The quoted sentences say what the papers report.
breast cancer (17 papers, 2018 to 2025). A primary or metastatic malignant neoplasm involving the breast. "In comparison, only 27% of GPT2 low expression breast cancers were flat to metastasis, indicating that GPT2 is associated with breast cancer metastasis." (PMID 36923530, 2023). "Interestingly, we also uncovered novel putative associations, such as the possible modulation by GPT2 of 2-hydroxyglutarate accumulation in breast cancer tissue (validation of this relationships would require further experimentation)." (PMID 29506475, 2018). "Elevated GPT2 expression is observed in proliferating breast cancer cells, and its inhibition reduces cancer cell survival." (PMID 41323791, 2025). "The δ receptor subunit GABRD is required for GPT2/GABA-induced metastasis; Gpt2 knockout results in reduced lung metastasis of Gpt2−/− breast cancer and prolongs survival in mice." (PMID 40722337, 2025). "In breast cancer, GPT2 serves as a pivot between glycolysis and glutaminolysis, and promotes tumorigenesis and stemness." (PMID 40416363, 2025). "Elevated GPT2 expression is observed in proliferating breast cancer cells, and inhibition of GPT2 activity reduces cancer cell survival." (PMID 41323791, 2025). "The change in GPT2 in murine mammary cancer cells expression was accompanied by the increase of the ATF4." (PMID 38808274, 2024). "Further analysis showed that the GPT2 high expression breast cancers were more aggressive, and 40% of breast cancers with GPT2 high expression were prone to metastasis." (PMID 36923530, 2023). "The knockout of Gpt2 to some extent extended the overall survival of tumor burden mice compared to the wildtype breast cancer mice model." (PMID 36923530, 2023). "Most importantly, both the tail vein model and Mammary gland conditional Gpt2-/- spontaneous tumor mouse models were used to evaluate the effect of GPT2 on breast cancer metastasis in vivo." (PMID 36923530, 2023). "And the GAD1 overexpression also partially recovered the GPT2 depletion-reduced breast cancer migration." (PMID 36923530, 2023). "The delta subunit GABRD is necessary for the GPT2/GABA-induced breast cancer metastasis in xenograft and transgenic mouse models." (PMID 36923530, 2023). "Cell migration and adhesion pathways were two of the top ten activated pathways, suggesting that GPT2 was involved in the metastatic process of breast cancer." (PMID 36923530, 2023). "Function analysis showed that CREB overexpression increased the GPT2 depletion-reduced breast cancer cell migration." (PMID 36923530, 2023). "PKC/CREB signaling was activated in response to GPT2-induced calcium influx and consequently promoted breast cancer metastasis." (PMID 36923530, 2023). "In the meantime, we found that GPT2 overexpression also accelerated the migration of breast cancer MCF7 cells." (PMID 36923530, 2023). "In contrast, GPT2 depletion reduced the migration of breast cancer MDA-MB-468 cells, representing a high endogenous GPT2." (PMID 36923530, 2023). "The upregulation of PODXL, MMP3 and MMP9 are believed to promote cell migration 48-50, suggesting CREB activation is critical for GPT2/GABA-induced breast cancer migration." (PMID 36923530, 2023). "GPT2 expression was increased in metastatic breast cancers compared to primary breast cancers (p < 0.001)." (PMID 36923530, 2023). "In this study, we found that GPT2 promoted breast cancer metastasis by activating the GABAA receptor, and the delta subunit is necessary for this activation." (PMID 36923530, 2023). "In contrast, the GABAA receptor inhibitor picrotoxin and CREB inhibitor 666-15 inhibited the GPT2-promoted breast cancer metastasis." (PMID 36923530, 2023). "Gpt2 knockout reduces the lung metastasis of the genetic Gpt2-/- breast cancer in mice and prolongs the overall survival of tumor burden mice." (PMID 36923530, 2023).
breast cancer (continued). "Under metabolic stress, GPT2 expression is upregulated in various tumor cells, including breast carcinomas, and the viability of pancreatic cancer cells was decreased when GPT2 activity was inhibited 13-16." (PMID 36923530, 2023). "For instance, GPT2 promotes tumorigenesis of breast cancer by activating sonic Hedgehog signaling, and abrogating GPT2 in triple-negative breast cancer can inhibit tumor growth and promotes autophagy." (PMID 36527113, 2022). "For instance, in breast cancer, GPT2-enriched exosomes activate BTRC to promote metastasis." (PMID 41323791, 2025). "Picrotoxin also inhibited GPT2-induced breast cancer cell migration." (PMID 36923530, 2023). "PKC activation was increased in breast cancer cells expressing GPT2 or treated with GABA." (PMID 36923530, 2023). "We previously found that GPT2 promotes tumorigenesis in breast cancer." (PMID 36923530, 2023). "In contrast, the CREB inhibitor 666-15 decreased the GPT2-promoted breast cancer cell migration." (PMID 36923530, 2023). "In addition, the calcium chelator BAPTA also significantly inhibited GPT2-induced breast cancer cell migration." (PMID 36923530, 2023). "Moreover, GABA recovered the migration and invasion ability of breast cancer cells depleted of GPT2." (PMID 36923530, 2023). "Also, α-ketoglutarate deriving from GPT2-dependent pyruvate to alanine conversion in breast cancer cells is required to drive collagen-based remodeling of the extracellular matrix in the lung metastatic niche." (PMID 37414778, 2023). "The GABA treatment recovered the GPT2 depletion-suppressed breast cancer metastasis." (PMID 36923530, 2023). "Moreover, the conditional media from GPT2 overexpressing BT549 cells significantly promoted the cell migration of breast cancer cells depleted of GPT2 compared to the media from parental cells." (PMID 36923530, 2023). "To determine whether GPT2 promotes breast cancer metastasis, we performed RNA sequencing on breast cancer BT549 cells." (PMID 36923530, 2023). "Glutamic pyruvic transaminase 2 (GPT2), also known as alanine aminotransferase 2 (ALT2) expression, has been shown to be associated with good prognosis in hepatocellular carcinoma and poor prognosis in breast cancer." (PMID 37958393, 2023). "To determine whether GPT2 promoting breast cancer cell migration depends on GABA, we assessed the migration and invasion capability by the wound healing evaluation and the transwell assay in BT549 cells treated with GABA." (PMID 36923530, 2023). "Although GPT2-mediated glutamate production has been shown to support cell proliferation in non-small cell lung cancer and breast cancer cell lines, it is the reverse reaction that produces α-KG, which is important for cell proliferation in the majority of colorectal and other cancers." (PMID 36179030, 2022). "Moreover, GPT2 promotes tumorigenesis of breast cancer cells by activating sonic hedgehog signaling." (PMID 35804447, 2022). "While the exact mechanisms underlying increased levels of 2-hydroxyglutarate in breast cancer cells are not all known, our results suggest that metabolic reprogramming changes the relationship between GPT2 and 2-hydroxyglutarate." (PMID 29506475, 2018). "Therefore, as a well-known transcription factor regulated by calcium signaling, CREB was chosen to determine whether GPT2/GABA promoted breast cancer metastasis via CREB activation." (PMID 36923530, 2023). "Furthermore, the wound healing assay, transwell evaluation, and invasion test showed that GPT2 overexpression significantly promoted migration and invasion of breast cancer BT549 cells; in contrast, depletion of GPT2 inhibited migration and invasion of breast cancer BT549 cells." (PMID 36923530, 2023). "Moreover, GABRD depletion inhibited GPT2-induced breast cancer cell migration." (PMID 36923530, 2023). "Thus, the intracellular calcium influx/concentrations were analyzed to determine whether calcium signaling mediates GPT2/GABA-regulated breast cancer cell migration." (PMID 36923530, 2023).
breast cancer (continued). "The overexpression of GPT2 results in an increase in GABA content and the GABAA-receptor-mediated promotion of metastasis in experimental breast cancer." (PMID 40722337, 2025). "In order to investigate the effect of GPT2 on breast cancer metastasis, we first introduced Gpt2 gene knockout C57BL/6 mice, and then mated with MMTV-PyMT mice to generate MMTV-PyMT; Gpt2+/- and MMTV-PyMT; Gpt2-/- mice." (PMID 36923530, 2023). "To exclude redox's effect on glutamine metabolism on breast cancer cell migration, we analyzed the cellular ROS (reactive oxygen species) by flow cytometry in BT549 cells overexpressing GPT2." (PMID 36923530, 2023). "And the gene expression profiles were analyzed by gene ontology analysis in breast cancer cells with or without GPT2 overexpression." (PMID 36923530, 2023). "Then, to further investigate the association of GPT2 with breast cancer metastasis, we first analyzed the GPT2 expression by IHC in breast cancer with or without metastasis." (PMID 36923530, 2023).
colorectal cancer (12 papers, 2016 to 2025). A primary or metastatic malignant neoplasm that affects the colon or rectum. "Previous studies in colorectal cancer showed that PIK3CA mutations reprogram glutamine metabolism by upregulating GPT2 in colorectal cancer cells, making these cancer cells more dependent on glutamine for their survival." (PMID 36010673, 2022). "PIK3CA mutations have been found to increase glutamate pyruvate transaminase 2 (GPT2) in colorectal cancer (CRC) cells." (PMID 34200820, 2021). "Furthermore, in PIK3CA-mutated colorectal cancer, GPT2-mediated generation of α-KG from glutamine is indispensable for cell growth." (PMID 41323791, 2025). "In PIK3CA-mutated colorectal cancer, GPT2-derived α-KG from glutamine is essential for cell growth." (PMID 41323791, 2025). "Furthermore, colorectal cancer cells harboring PI3KCA mutations like HCT116 cells display an increased expression of glutamate pyruvate transaminase 2 (GPT2) making them more dependent on glutamine." (PMID 36302756, 2022). "Similarly, colorectal cancer with oncogenic PIK3CA mutations exhibits strong dependency on glutamine due to up-regulated expression of glutamate pyruvate transaminase 2 (GPT2)." (PMID 35178349, 2022). "PIK3CA mutations reprogram glutamine metabolism by upregulating GPT2 in colorectal cancer cells." (PMID 35804447, 2022). "Also, aminooxyacetate (AOA) suppresses tumor proliferation of colorectal cancer with PIK3CA mutations by inhibiting enzymatic activity of GPT2." (PMID 35804447, 2022). "In colorectal cancer (CRC), PIK3CA mutations have been shown to reprogram glutamine metabolism by upregulating glutamate pyruvate transaminase 2 (GPT2), thereby increasing tumor cell dependence on glutamine." (PMID 41425618, 2025). "In colorectal cancer, it dictates glutamine dependency by modulating expression of glutamate pyruvate transaminase 2 (GPT2), enhancing the conversion of glutamate to aKG, and facilitating increased TCA utility." (PMID 34283054, 2021). "Here we show that PIK3CA mutations reprogram glutamine metabolism by upregulating glutamate pyruvate transaminase 2 (GPT2) in colorectal cancer (CRC) cells, making them more dependent on glutamine." (PMID 27321283, 2016). "In addition to the regulation of GOT1 by KRAS, oncogenic PIK3CA mutations also have been reported to mediate metabolic reprograming of glutamine in colorectal cancer (CRC) by upregulating glutamate pyruvate transaminase 2 (GPT2)." (PMID 33194749, 2020).
acute myeloid leukemia (4 papers, 2024 to 2025). Acute myeloid leukemia (AML) is a group of neoplasms arising from precursor cells committed to the myeloid cell-line differentiation. "In acute myeloid leukemia (AML), IMP2 stabilizes key mRNAs, including MYC, GPT2, and SLC1A5, that are essential for glutamine uptake and metabolism, fueling the TCA cycle and supporting AML cell proliferation and survival." (PMID 40141058, 2025). "IGF2BP2 recruits proteins such as eIF4E and eIF3A to MYC, GPT2, and SLC1A5 mRNA, regulating glutamine metabolism in acute myeloid leukemia and modulating the immune response of macrophages through epigenetic reprogramming." (PMID 39726589, 2024). "IGF2BP also stabilizes MYC, GPT2, and SLC1A5 mRNA to promote acute myeloid leukemia (AML) development." (PMID 41041073, 2025).
colon cancer (4 papers, 2015 to 2024). "Interrupting this link using RNAi against cytosolic alanine transaminase (GPT2) was demonstrated to impair oxygen metabolism, cell proliferation, and tumor growth in colon cancer." (PMID 39518046, 2024). "Maintenance of glutamine anaplerosis and catabolism in cancer cells via increased GPT2 activity is essential for oncogenic KRAS-induced anchorage independent growth, as demonstrated by knockdown of GPT2 expression in HCT116 colon cancer cells." (PMID 25621173, 2015). "In colon cancer cell lines, oncogenesis involves upregulation of LDH isoform A (at the expense of LDHB) and glutamate-pyruvate transaminase 2 (GPT2)." (PMID 32013066, 2020).
glioblastoma (4 papers, 2018 to 2023). The most malignant astrocytic tumor (WHO grade IV). "Genes coding for GLUD1 and GPT2 expression levels varied according to the grade of malignancy, being downregulated in glioblastoma, and upregulated in lower grades of astrocytoma (AGII–AGIII)." (PMID 33910646, 2021). "Through analyzing glutamate-linked aminotransferases, we here identified glutamate pyruvate transaminase 2 (GPT2) as a direct HIF-2 target gene in human glioblastoma (GBM)." (PMID 36010673, 2022). "In glioblastoma, particularly in the mesenchymal subtype, the downregulation of both genes and proteins (GLUD1 and GPT2) increases the source of glutamate for GSH synthesis and enhances tumor cell fitness due to increased antioxidative capacity." (PMID 33910646, 2021).
microcephaly (4 papers, 2022 to 2024). A congenital or acquired developmental disorder in which the circumference of the head is smaller than normal for the person's age and sex. "In agreement with this, GPT2 deficiency results in smaller soma sizes and slightly depolarized CA1 pyramidal neurons as well as microcephaly in both mice and human patients with GPT2 mutations as previously demonstrated." (PMID 39604975, 2024). "In family 11, two affected individuals were found to have a missense mutation (c.815C > T; p.Ser272Leu) in GPT2, which is associated with neurodevelopmental disorder with microcephaly and spastic paraplegia (OMIM 616281)." (PMID 39281811, 2024). "In humans, autosomal recessive mutations in glutamate-pyruvate transaminase 2 (GPT2) cause a neurological syndrome characterized by intellectual disability, microcephaly, and progressive motor symptoms." (PMID 37876541, 2023). "In humans, GPT2 autosomal recessive mutations cause a neurological syndrome characterized by intellectual disability, microcephaly, and progressive motor symptoms." (PMID 35196498, 2022). "Recessive mutations in the GPT2 gene have been described in a human neurological syndrome involving intellectual and developmental disability (IDD), post-natal microcephaly, and spastic paraplegia, coupled with small stature." (PMID 35196498, 2022).
Obesity (4 papers, 2021 to 2024). Accumulation of substantial excess body fat. "We also observed lower expression of GPT2 in active and inactive beige adipocytes with FTO obesity-risk genotype as compared to risk-free allele carriers." (PMID 37416800, 2023). "We also revealed that one-carbon metabolism pathway, in which SHMT1 and GPT2 participate, was less expressed in active beige adipocytes with FTO obesity-risk alleles." (PMID 37416800, 2023). "Lower expression of GPT2 and glutamine consumption may contribute to the downregulation of pyruvate metabolism and TCA cycle pathway in active beige adipocytes with obesity-risk alleles." (PMID 37416800, 2023).
bladder cancer (3 papers, 2022 to 2025). "Investigating and elucidating the mechanism of GPT2 in bladder cancer (BCa) provides novel evidence for further understanding the pathogenesis of bladder cancer and developing subsequent therapeutic strategies." (PMID 41323791, 2025). "GPT2 plays a key role in glutamine-driven replenishment of intermediates for the TCA cycle in bladder cancer cells." (PMID 36499136, 2022). "UCA1, hnRNP I/L, and GPT2 functionally facilitate tumor growth and are involved in glutamine-driven anaplerosis in bladder cancer cells." (PMID 36499136, 2022). "UCA1 upregulates glutamate pyruvate transaminase 2 (GPT2) expression through interaction with heterogeneous nuclear ribonucleoprotein I/L, and promotes glutamine driven bladder cancer reperfusion." (PMID 37215997, 2023).
glioma (3 papers, 2024 to 2025). A benign or malignant brain and spinal cord tumor that arises from glial cells (astrocytes, oligodendrocytes, ependymal cells). "It has been suggested that hypoxic U87 glioma cells produce α-KG from glutamine, a reaction catalyzed by glutamic pyruvate transaminase 2 (GPT2), given the increased intracellular concentrations of glutamine and glutamate." (PMID 38786726, 2024). "GTP2 is induced by HIF2α in human glioma cells under hypoxic stress, and GPT2 inhibition decreases cell proliferation and migration in vitro and in vivo." (PMID 38786726, 2024). "In addition, higher expression of OGT, FOXC1, ASNS, GPT2, CBS, or FTH1 was also associated with poorer outcomes in clinical cases with renal clear cell carcinoma or glioma." (PMID 40416363, 2025). "The results showed a significant negative correlation between GPT2 expression and promoter methylation in most cancers, except ovarian cancer and glioma." (PMID 41323791, 2025).